CD47 (CD47 molecule)
Diseases named in the same sentence as CD47 in open-access papers (continued):
Sharing a sentence is not in itself a finding about the gene and the disease.
tumor (continued). "Additionally, high CD47 expression correlated with increased PD-L1, and patients with concurrent high CD47 and positive PD-L1 of tumor cells had the shortest PFS, although this trend was not statistically significant." (PMID 41811881, 2026). "However, CD47, an anti-phagocytic “do not eat me” signal, is often highly expressed on tumor cells, counteracting the effects of CALR." (PMID 40356601, 2025). "Mechanistically, tumor cells exhibit strong adhesive properties and overexpress membrane proteins, such as CD47, CD44, and various integrins, which enable immune evasion, intercellular adhesion, and the recruitment of circulating cells—processes that contribute to tumor progression and metastasis." (PMID 40624508, 2025). "In addition to directly regulating the expression of CD47, MYC may further help tumor cells escape phagocytosis by regulating the expression of argininosuccinate synthetase 1 (ASS1), a key enzyme in arginine biosynthesis." (PMID 40732268, 2025). "However, the CD47- SIRPα and the PD1-PD-L1 pathways are part of a more complex tumor microenvironment, which does not only include macrophages and T cells, but is also constituted by B cells, dendritic cells, stromal cells, blood vessels, and extracellular matrix." (PMID 40369208, 2025). "Thus, the simultaneous activation of NFκB and JAK/STAT signaling in TRIM28-deficient cells provides a plausible mechanistic link to enhanced expression of CD24/CD47, suggesting that TRIM28 modulates tumor–immune interactions through coordinated regulation of cytokine and adhesion pathways." (PMID 41303350, 2025). "Additionally, cancer cells could express certain “marker of self” proteins (like CD44, CD47, and CD200) and immune checkpoints (PD‐L1), which assist in evading immune‐mediated tumor clearance." (PMID 40600457, 2025). "Furthermore, the anti–CD47/SIRPα axis not only inhibits local irradiated tumor cells but also inhibits distant non-irradiated tumor cells." (PMID 40835598, 2025). "Moreover, oAd-CD47 significantly decreased the number of MDSCs and Tregs in the TME and effectively reversing the increased expression of PD-1 and Tim-3 on CD8+T cells, thereby enhancing anti-tumor T cell responses." (PMID 40814015, 2025). "Therefore, in this study, we aimed to combine a checkpoint inhibitor against the CD47–SIRPα axis that has not been previously utilized in combination with CAR-NK therapy to enhance the anti-tumor efficacy of CDH17-targeted CAR-NK cells." (PMID 40487639, 2025). "For example, TUG1 sponges miR-141 and miR-340, resulting in increased PD-L1 and CD47 on tumors, as well as TUG1 binding the transcription factor YBX1, further enhancing the transcription of these immune-evasive signals, thus establishing a self-perpetuating feedback loop that promotes tumor escape." (PMID 41154428, 2025). "Consistently, Tumor Immune Estimation Resource (TIMER)-based analysis of TCGA-COAD data confirmed increased infiltration of CD8+ T cells, macrophages, and dendritic cells in CD47-high tumors, supporting a potential role for CD47 in modulating an immunosuppressive TME." (PMID 41514569, 2025). "Additionally, flow cytometry analysis of PD-L1 and CD47 co-expression in various cell populations within the TME, along with splenic immune cells as controls, revealed that tumor-infiltrating Treg cells exhibited the highest levels of PD-L1 + CD47 + co-expression." (PMID 41402667, 2025). "Supporting this hypothesis, immunoblotting of tumor cell lysates and IHC analysis of in vivo LLC graft tissues revealed reduced CD47 expression and increased staining of CD11b in RASON KO tumors, which was consistent with the increased infiltration of macrophages in RASONlow human samples." (PMID 40128846, 2025). "We do not have MC38 tumor growth data with combined CD47-KO and RT in WT mice." (PMID 41296731, 2025).
tumor (continued). "Thus, through modulating ncRNA-RB1 and MIAT expression, tumor cells may impair antigen uptake by disrupting the balance between the pro- and anti-phagocytic signals provided by CRT and CD47." (PMID 40429961, 2025). "Overcoming TAM-mediated resistance involves strategies targeting their recruitment (e.g., CCL2/CCR2 blockade), survival/differentiation (e.g., CSF-1/CSF-1R inhibition), function (e.g., blocking “do not eat me” signals like CD47), or attempting to repolarize them towards an anti-tumor M1-like state." (PMID 40458806, 2025). "In 191 resected NSCLC specimens, CD47 was more frequently overexpressed in females, never-smokers, and lung adenocarcinoma patients, significantly correlating with EGFR mutations but inversely with PD-L1 levels and tumor mutation burden." (PMID 40079009, 2025). "To validate whether our system could identify tumor-intrinsic modulators of phagocytosis, we knocked out the expression of CD47, a well-established do-not-eat-me signal, in Panc02-Fc cells." (PMID 41243973, 2025). "However, mice receiving NDV-vectorized CD47 blockade had a higher incidence of CR compared to those receiving NDV alone, in addition to delayed tumor growth; 66.7% (4/6) and 42.9% (3/7) of mice receiving NDV-αCD47 and NDV-SIRPα-Fc experienced CR, compared to 33.3% (2/6) in those receiving NDV alone." (PMID 41322194, 2025). "In tumor cells not expressing QPCTL, there is reduced pyroglutamination in CD47- SIRPα binding and enhanced macrophage phagocytosis of tumor cells.1051,1052 Phase 1 or 2a studies evaluating QPCT or QPCTL inhibitors for neurodegenerative diseases reported no significant toxicity." (PMID 40055311, 2025). "These clinical data suggest that an optimized CD47 blockade, especially when combined with ICI, may enhance antigen presentation by promoting macrophage-mediated phagocytosis and subsequent presentation of tumor antigens to T cells." (PMID 40508202, 2025). "Additionally, tumour stem-like cells residing in perivascular niches express CD47, delivering a “do-not-eat-me” signal to phagocytes and synergising with down-regulated calreticulin to constrain macrophage-mediated clearance." (PMID 40995359, 2025). "However, some studies indicated that CD47 blockade can have different radiotherapy effects between normal and tumor cells." (PMID 40835598, 2025). "Nevertheless, it should be noted that the expression of CD47 is not exclusive to tumour cells, and inhibiting CD47 systemically may result in certain toxicities that need to be considered." (PMID 40385641, 2025). "Thus, hypoxia induced tumor derived exosomal ZEB1 was demonstrated to promote immune evasion and escape from innate immune surveillance in cervical squamous carcinoma cells by modifying the activity of the CD47/SIRPα/STAT3 axis." (PMID 39928285, 2025). "Similarly, pairing CD47 blockade with DNA damage response therapies, including poly (ADP-ribose) polymerase (PARP) inhibitors, has shown synergistic potential by promoting immunogenic stress responses and facilitating tumor cell recognition." (PMID 41179296, 2025). "SIRPα-VEGFR1 could achieve similar anti-tumor effects as a combination therapy and showed that co-targeting CD47 and angiogenesis did not intervene with their individual effects." (PMID 39335665, 2024). "Interestingly, we find that the therapeutic efficacy of CD47-SIRPα blockade is highly dependent on tumor cell-intrinsic IFN-I signaling, but not IFN-II signaling." (PMID 38982116, 2024). "However, accumulating data have shown that CD47 blockade as a single modality has no or low anti-tumor activity in solid tumors." (PMID 38992659, 2024). "The binding of tumor cell CD47 to macrophage SIRP-α leads to the activation and phosphorylation of the SIRP-α ITIM motif, and recruitment of SHP-1 and SHP-2 phosphatases, which inhibit tumor cell phagocytosis by preventing the accumulation of myosin IIA at phagocytic synapses." (PMID 39065562, 2024).
tumor (continued). "There was no significance difference in the expression levels of PD-L1 (p = 0.676) and CD47 (p = 0.647) in normal epithelia at keratinized and non-keratinized sites on the same slides, indicating that the findings were tumor-specific." (PMID 38612630, 2024). "Consequently, we strongly suggest that CD47 might impair CD8 + T cell function and so negatively impact tumor patients' prognosis." (PMID 38720108, 2024). "Notably, in preclinical research related to OC, suppressing the expression of CD47 and CD24 or blocking them with anti-CD47 and anti-CD24 mAbs was found to enhance macrophage-mediated phagocytosis, thus resulting in a significant reduction in the growth of xenograft tumours." (PMID 38702326, 2024). "Additionally, we used a multivariate Cox proportional hazards model to assess the prognostic relevance of CD47 expression with respect to several clinicopathological variables, including histological subtype (LPS, MFS, UPS and varia), tumor grade, metastases, sex, and age." (PMID 38493445, 2024). "Importantly, CD47 expression was extremely high in SKOV3, SKBR3, DLD-1, and ASPC1 tumor cells, and coculture with these tumor cells significantly increased SIRPα expression in UTD and CAR macrophages, whereas CAR-shSIRPα macrophages maintained low SIRPα levels." (PMID 39379603, 2024). "While Bifidobacterium alone may not directly inhibit tumor growth systemically, it can boost the antitumor effects in mice unresponsive to CD47 blockade." (PMID 38835386, 2024). "CD47, a “do not eat me” signal, prevents tumor phagocytosis by macrophages." (PMID 38399416, 2024). "Due to the specific interactions between the RS17 peptide and CD47 on tumor cells, as well as the innate tumor-homing abilities of the M1 EVs, the manufactured hybrid nanovesicles (LEV-RS17) displayed robust tumor-targeting ability and increased drug accumulation at tumor sites." (PMID 39033108, 2024). "However, anti-CD47 therapies still encounter many setbacks in terms of selectivity, efficacy, and safety profile as CD47 is expressed not only on tumor cells but also on non-malignant cells." (PMID 39712032, 2024). "Monotherapy with CD47 blockade usually could not fully inhibit the growth of solid tumors due to the “antigen sink” effect and the heterogeneity of the tumor microenvironment." (PMID 39335665, 2024). "In addition, similar to CD-47 combination therapy, applying CD40 receptor agonists after inhibiting the CSF-1 receptor can remarkably enhance T-cell activity, thereby boosting anti-tumor immune responses." (PMID 39169402, 2024). "We also witnessed that CD47 mRNA expression is higher in the “inflamed” tumor, which implies that CD47 might act as a negative feedback factor to counter anti-tumor immunity." (PMID 39335665, 2024). "Here, we investigate the combination of a CD47 blockade (magrolimab, MAG) to inhibit the anti-phagocytic signal and a chemotherapy regimen (doxorubicin, DOX) to enhance the pro-phagocytic signal to induce macrophage phagocytosis of ES cells in vitro and inhibit tumor growth and metastasis in vivo." (PMID 38992659, 2024). "Therefore, in the ID8-Defb29/Vegf-A model, blocking the CD47 axis to turn off the “don’t eat me signal” is not sufficient to slow tumor progression and achieve durable anti-tumor effects, especially durable adaptive immune responses." (PMID 38832992, 2024). "As a single agent, the anti-CD47 antibody produced no significant inhibition of tumor growth." (PMID 38483480, 2024). "Because of its distinctive design and diverse modes of action, the CD38/CD47 BsAb has the potential to augment antitumor efficacy in individuals with CD38+ malignancies in comparison to anti-CD38 mAbs by effectively addressing primary and acquired tumor escape mechanisms of resistance." (PMID 38983860, 2024). "Moreover, the effective dosage of CD47 antagonists may require adjustments in scenarios where tumor cells express both SIRPα and thrombospondin-1 (TSP-1), both of which disrupt the CD47-SIRPα interaction." (PMID 39040441, 2024).
tumor (continued). "However, in PBTs the limited presence of tumour-associated antigens (TAAs) due to the low TMB and the increased release of CD47 often detected in MYC-amplified tumours that reduce phagocytosis lead to low levels of antigen presentation and, consequently, lower anti-tumour immunity." (PMID 38732225, 2024). "Specifically, the average tumor weights were 1.07 g for the antibody combination group and 0.33 g for the PAC-SABIs group, reflecting a unique PAC-SABIs functionality of concurrently inhibiting CD47 and CD24 signaling, coupled with their intrinsic self-assembly ability within the complex TME." (PMID 38971872, 2024). "Since RTX-IgG2 was capable of altering and reducing the expression of CD47 on the target Granta-519 cells, we hypothesized that a pre-treatment of Granta-519 cells with RTX-IgG2 would enhance the efficacy of other tumor-targeting mAbs to induce ADCP." (PMID 39712032, 2024). "While we could not confirm prolong infectivity within tumor tissue due to CD47 expression, the dual-armed MyxV showed significant tumor growth inhibitory effects of the B16F10 syngeneic mouse model compared to parental MyxV and to each single-armed MyxV." (PMID 37835397, 2023). "Additionally, some studies have explored the use of engineered immune cells that express a modified SIRPα receptor with higher binding affinity for CD47 or CD47-targeted CAR T-cell therapy to directly kill cancer cells and enhance the anti-tumor immune response." (PMID 38188674, 2023). "In depth, ferroptosis would change tumor cells into “altered self” or “missing self” with the downregulation of the “do not eat me signals” such as CD47 on the surfaces of tumor cells, or through mimicking microbial antigens by releasing DAMPs like oxidized lipids." (PMID 37325669, 2023). "Moreover, a function-blocking CD47 antibody B6H12 is capable of modulating multiple EVs-mediated signals between breast tumor cells and ECs that promote the proliferation and metastasis of tumor cells." (PMID 37666809, 2023). "On the other hand, though RAGA knockdown dramatically increased the tumor growth compared to that of control, the promoting effect was repressed by CD47 blockade, supporting that the oncogenic effect of RAGA knockdown is largely due to upregulated CD47 accumulation." (PMID 36823443, 2023). "In addition to the CD47/SIRPα cascade, CD40 agonists re-educate TAMs into M1 macrophages to restore cancer immune surveillance, and the combination therapy of anti-PD1/PD-L1 and anti-CD40 also enhances anti-tumor efficacy." (PMID 36845095, 2023). "Most importantly, the anti-CD47 arm of 6MW3211 selectively binds to CD47 on tumor cells but not CD47 expressing on RBCs, which may enable the good safety profile of 6MW3211 in NHP studies and further human clinical trials." (PMID 36593962, 2023). "Moreover, CD47 is highly expressed in patients with low tumor CD8+ T cell infiltration, confirming its negative role in the antitumor immune response." (PMID 36829496, 2023). "Compared with untreated tumor-bearing mice, the low-dose anti-CD47 antibody treatment alone could not inhibit tumor growth." (PMID 37723178, 2023). "CD47 is known as a “do not eat me” signal that, following its binding with SIRPα on macrophages, prevents the macrophage-mediated phagocytosis that represents the engulfment of tumor cells by phagocytosis-specialized macrophages." (PMID 36829496, 2023). "Systemic administration of Bifidobacterium can lead to its accumulation in the tumor, converting non-responder mice into responders to anti-CD47 immunotherapy in a stimulator of interferon genes (STING) and interferon-dependent manner, ultimately promoting the efficacy of anti-CD47 immunotherapy." (PMID 37381018, 2023). "OXP and anti-CD47 failed to reduce Treg content in the spleen and tumor microenvironment; this failure could be the reason why in this treatment strategy, despite an increase in CD8+ T cells, we didn't see the therapeutic response." (PMID 36774400, 2023).
tumor (continued). "Consistent with nongenetic cellular heterogeneity in vitro, HARA cell tumors formed in the lungs of Rag2–/–Il2rg–/–Cd47–/– recipient mice were also heterogeneous with respect to calbindin protein, with clusters of positive and negative cells in the same tumor nodule." (PMID 37192000, 2023). "Owing to the presence of p-selectin and membrane proteins such as CD47, CD55, and CD59 on their surface, they can not only evade phagocytosis by Mø and prevent activation of the complement system but also recognize injured blood vessels as well as circulating tumor cells (CTCs)." (PMID 37128288, 2023). "However, macrophages do not phagocytose tumor cells because of high levels of CD47, a cluster of differentiation 47, in tumor cells, which inhibits phagocytosis vis interaction with SIRPα, signal regulatory protein α." (PMID 37686603, 2023). "Next, we aimed to determine whether combining therapy with anti-CD47, anti-PD-L1, and immunological death inducer chemotherapeutic agents (OXP or FOLFOX) could generate anti-tumor response compared to chemotherapy or bicombinig therapy with chemotherapy and checkpoint blockers." (PMID 36774400, 2023). "CD47 is a membrane glycoprotein signal, which means “do not eat me” on tumor cells." (PMID 36721212, 2023). "The ideal CD47-based therapeutic modalities could specifically activate macrophage phagocytosis of tumor cells but not RBCs followed by T cell activation." (PMID 36593962, 2023). "Moreover, humanized anti-CD47 therapeutic antibodies used to treat human tumor xenografts do not recognize CD47 on mouse cells, which would otherwise be bound by CD47 mAbs due to its ubiquitous expression." (PMID 37958404, 2023). "Hence, CD47 blocking in CD8+T cells and tumor cells may increase tumor clearance and patient survival through metabolic alteration of tumor and immune cells." (PMID 37275901, 2023). "The CD47–SIRP interaction promotes the inhibition of myosin-IIA build-up at the level of the phagocytic synapse, as well as the recruiting of downstream Src homology-2 domain-containing protein tyrosine phosphatases (SHP-1 and SHP-2), thus preventing macrophage-mediated tumor phagocytosis." (PMID 37894427, 2023). "CD47 interacts with several receptors and molecules, including TSP-1 and SIRPα, to activate downstream pathways such as Akt/mTOR, NF-κB, PI3K/Akt, RhoA/ROCK, and others, to regulate cellular processes such as tumor cell survival, invasion, angiogenesis, cell migration, and apoptosis." (PMID 38188674, 2023). "Disruption of CD47‐SIRPα signaling in the presence of prophagocytic signals can lead to enhanced phagocytosis of tumor cells, resulting in a direct antitumor effect; agents targeting this pathway have shown efficacy in non‐Hodgkin lymphoma (NHL) and other tumor types." (PMID 37206279, 2023). "Additionally, several well-designed BsAbs have been created, such as IMM2902 for CD47-Her2, IMM0306 for CD47-D20, and IBI322 for CD47-PD-L1, which effectively inhibit the CD47-SIRPα signal and enhance tumor cell phagocytosis without significant impact on RBCs." (PMID 38125492, 2023). "The results of this study indicate that upregulation of KNL1 expression may be adverse to the antitumor immune response of the body, and it is significantly positively correlated with the immunotherapy target CD47, suggesting that KNL1 may be a potential immunotherapy target for tumor immunotherapy." (PMID 36776306, 2023). "In addition to PD-1/PD-L1, the immunologic checkpoint, CD47, which is expressed on numerous malignant tumor cells, operates as a “do not eat me” signal to block DCs from phagocytosing tumor cells." (PMID 37144580, 2023). "Binding to CD172a (the signal regulatory protein α, SIRPα) on macrophage, CD47 on tumor cells can send the inhibitory signal “do not eat me” to macrophages so as to maintain the immune tolerance of own cells, prevent tumor cells from being phagocytized, and inhibit tumor antigen presentation." (PMID 37241964, 2023).